VIM (vimentin)
Diseases named in the same sentence as VIM in open-access papers (continued):
Sharing a sentence is not in itself a finding about the gene and the disease.
cancer (continued). "We used pan-cancer expression data to find 14-LncRNAs that had a high correlation with the EMT markers VIM, CDH1, FN1, SNAI1, and SNAI2." (PMID 36120580, 2022). "There are accumulating evidence supports that EMT plays an important role in cancer cell migration and invasion, which can be regulated by E-Cadherin, N-Cadherin and Vimentin." (PMID 36590309, 2022). "Immunofluorescence images showed cytokeratin 19 (CK19)-positive cancer glands intermixed with vimentin-positive CAFs in the CIPCO." (PMID 35565206, 2022). "Inhibition of FTO with shRNAs was sufficient to suppress the expression of ZEB1 and Vimentin, promote E-cadherin expression levels, and attenuate docetaxel resistance of cancer cells following SN-exo incubation." (PMID 36302751, 2022). "The small-molecule compound R491 binds to vimentin, impairs vimentin-mediated MVBs transport and exosome release, and thus inhibits the motility of various cancers." (PMID 36320056, 2022). "This was more apparent in tumors invaded by a large number of NK cells (hot areas), wherein strong vimentin signals were detected in the cancer cells around the NK cells." (PMID 36032170, 2022). "In conclusion, we have shown that vimentin downregulated keratin expression and, by implication, suppressed differentiation, thereby enhancing cancer progression and metastasis." (PMID 36552797, 2022). "OCT4+vimentin+ cancer cells also stratified patients by OS when combined with PD-1 expression and snail." (PMID 36358805, 2022). "The results of this study are expected to gain new findings about the potential of natural ingredients as alternative candidates for effective cancer therapy by altering migration and expression of Snail, Vimentin, and E-Cadherin in HeLa cancer cells." (PMID 36479442, 2022). "N-cad and vimentin are well-known EMT markers, and their overexpression is frequently associated with the strengthening of cancer cells’ migratory and invasive abilities." (PMID 35409350, 2022). "Among them, seven genes (FHL1, SELL, VIM, IGFBP7, TNFAIP3, LCP2, and SLC7AB) were associated with the cancer-immunity cycle." (PMID 35565437, 2022). "Although pan-cancer analysis showed overexpression of VIM in most cancer types, its overall survival rate was promising, with 65.3 months of life expectancy in patients, thus making it an attractive diagnostic biomarker for aggressive stages of GBM." (PMID 35571016, 2022). "Overall, vimentin expression and function differ in various types of cancer, and vimentin as a potential molecular target for the treatment of cancer has been proposed." (PMID 35320951, 2022). "Post-translational modifications and functions of the cell-surface and extracellular vimentin have been studied extensively in processes involved in angiogenesis in both normal and cancer cells." (PMID 35207438, 2022). "Providing an active regulation of cell size coupled to resistance to autophagy is, obviously, an additionally important and advantageous function of vimentin when present in cells in dynamic transition or in cancer cells." (PMID 36099296, 2022). "Oxymatrine significantly decreased MMP-9, MMP-2, and vimentin and increased the E-cadherin level, demonstrating its ability to stop migration and invasion of the cancer cells." (PMID 35805049, 2022). "Activated STAT-3 triggers EMT, decreasing E-cadherin and increasing vimentin expression, thus inducing proliferation, migration and invasion of cancer cells." (PMID 35703345, 2022). "A stable cell line was selected from cells with knocked-down vimentin and was then co-cultured with NK cells for 24 h (the ratios of cancer cells to NK cells were 1:0.25, 1:0.5, 1:1, 1:3, and 1:6)." (PMID 36032170, 2022). "Altogether, these results support a role for ITGB2 and VIM in the SMAD3-dependent pro-invasive properties of cancer cells that are accentuated by hypoxic conditions." (PMID 35681731, 2022).
cancer (continued). "BPL2 appears to affect the transcription factor of EMT, disturbs vimentin expression, and ultimately inhibits cancer cell growth, invasion, and migration." (PMID 36547923, 2022). "Recent reports suggest that the post-transcriptional regulation of vimentin can also play a crucial role in cancer progression." (PMID 35207438, 2022). "Another study also showed that knockdown of vimentin in cancer cells makes them less sensitive to WFA." (PMID 36669020, 2022). "Cancer cell migration and invasion were suppressed along with epithelial-intermediate metastatic markers Snail and Vimentin." (PMID 36182900, 2022). "Their study revealed that β‐catenin+ cancer cells accompanied by the induction of E‐cadherin and vimentin exist in various metastatic patients." (PMID 35601657, 2022). "In other studies, Ets-1 was shown to regulate EMT and cancer cell invasion by promoting key EMT gene expressions such as vimentin, slug." (PMID 35789155, 2022). "In summary, we found that when immune cells attack cancer cells, the cancer cells resist immune cytotoxicity through upregulated vimentin and actin reorganization." (PMID 36032170, 2022). "Histologically, a loss of E-cadherin is more commonly observed in poorly differentiated PDAC while in contrast, 45% of PDAC cases had vimentin expressed in 1–95% of cancer cells, and 27.5% had vimentin expressed in 10% or more of the cancer cells." (PMID 35629168, 2022). "In sum, these data suggest PRMT5‐mediated sDMA modification negatively regulates the stability of vimentin, and the stabilized vimentin compels the invasion of MTAP‐deleted cancer." (PMID 35766227, 2022). "Accordingly, cancer cells upregulate the expression of CXCR4 with increased vimentin and decreased E-cadherin upon sensing CAF-produced CXCL12 in a coculture system." (PMID 36268282, 2022). "The silence of AKT1 not only abolished the properties of metastasis but also inhibited the expression of epithelial to mesenchymal transition markers, such as vimentin protein which is related to invasive cancers." (PMID 35646655, 2022). "Vimentin overexpression in different cancer cell lines and tissues was shown to be an independent positive prognostic factor for poor survival in patients with resected NSCLC." (PMID 35684095, 2022). "Treatment with ATRA significantly downregulated ZEB-1, fibronectin, and vimentin in cancer cells in CIPCOs." (PMID 35565206, 2022). "To recapitulate the process of EMT in cancer cells where keratin expression is suppressed and vimentin expression is instigated, we first decided to identify cancer cell lines devoid of vimentin." (PMID 36552797, 2022). "Increased vimentin changes cell shape and increases cell motility, promoting the metastasis of cancer cells." (PMID 35770085, 2022). "Western blot analysis was first conducted to investigate the expression of the epithelial marker (E‐cadherin) and mesenchymal marker (Vimentin) in NSCLC cancer cells." (PMID 36192568, 2022). "EpCAM, CK, and vimentin are the most commonly used molecular markers to identify CTCs and have been verified in several cancers." (PMID 35740311, 2022). "This is important for vimentin to be considered as a therapeutic target to inhibit cancer growth and spread." (PMID 36185255, 2022). "Remarkably, there was more intense vimentin staining (2–3+) in the poorly differentiated cancer cells (poor) at the edges of tumors than in the well-differentiated cells (well; 0–1+)." (PMID 36012449, 2022). "Vimentin, a cytoplasmic intermediate filament protein, has been recently identified to be a prognostic biomarker in some cancers." (PMID 35320951, 2022). "The enhanced expression of CXCL12, HGF, MMPs, and TGF-β in irradiated fibroblasts was found to increase invasion and EMT in cancer cells as indicated by the increased expression of vimentin, snail and beta-catenin, and decreased E-cadherin expression." (PMID 36010899, 2022).
cancer (continued). "The vimentin expression correlated significantly with differentiated states of oral precancers and cancers." (PMID 35498535, 2022). "Increased age was correlated to the vimentin expression mainly because of higher incidence of cancers in subjects with increasing age." (PMID 35498535, 2022). "Co-immunoprecipitation-MS analysis revealed that p62, a signaling adaptor frequently overexpressed in cancer and functioning as a tumor metastasis promoter, positively interacts with VIM." (PMID 36278695, 2022). "We conclude that Montanide ISA 720 shows potential to be used as an adjuvant for vaccination against extracellular vimentin for future clinical studies in cancer patients." (PMID 35681575, 2022). "Most studies so far have focused on actin reorganization regulating NK cell function, and our study showed that interference with actin reorganization and vimentin expression affected the ability of NK cells to kill cancer cells." (PMID 36032170, 2022). "As far as the difference of vimentin expression between ERBB2d16 high and low groups, it was also reflected partially by the density of vimentin-positive cancer cells." (PMID 35463314, 2022). "Epithelial-mesenchymal transition (EMT) and inhibition of Wnt/β-catenin signalling pathway contribute to migratory potential of cancer cells, alongside with overexpression of promigratory/invasive proteins: N-cadherin, Snail, vimentin, and β-catenin." (PMID 35910272, 2022). "In summary, the accumulation of actin filaments and the upregulation of vimentin were involved in the response of cancer cells to immune cells." (PMID 36032170, 2022). "Since one of the main mechanisms underlying metastasis is increased EMT of cancer cells, we measured EMT in the model by assessing the ratio of expression of the mesenchymal marker vimentin to the epithelial marker E-Cadherin." (PMID 36591282, 2022). "The EMT process is very complex, mediated by transcription factors such as SNAIL, ZEB, and Twist, activating mesenchymal markers (including N-cadherin, β-catenin, Fibronectin, and Vimentin) that play an important role in enhancing cancer cell motility." (PMID 36160416, 2022). "Epithelial–mesenchymal transition, which is characterized by reduced E‐cadherin and increased N‐cadherin and vimentin expression, has shown a critical role in cancer invasion and metastasis." (PMID 35229451, 2022). "The intermediate filament vimentin is widely used as a canonical marker of EMT and associated with cancer metastasis." (PMID 35766227, 2022). "β-catenin in cooperation with hTERT regulates transcription of Vimentin, so deregulation of all those proteins leads to preventing cancer progression." (PMID 35260633, 2022). "Because EMT is another hallmark of cancer metastasis, we investigated the effect of Olt on EMT markers, i.e., β-catenin and vimentin, after treatment with the Olt." (PMID 36231019, 2022). "Targeting of extracellular vimentin presents therefore an anti-angiogenic immunotherapy strategy against cancer." (PMID 35606362, 2022). "Meanwhile, highly concentrated fibrinogen induces epithelial-mesenchymal transition, which increases cancer cell invasion and metastasis using a cell line model by increasing vimentin expression and decreasing E-cadherin expression." (PMID 36042905, 2022). "Several reports have shown that motile and invasive cells express higher levels of vimentin and its absence attenuates migration of cancer cells." (PMID 36552797, 2022). "Vimentin is a multi-factorial protein involved in the migration of cancer cells that have undergone epithelial-mesenchymal transition." (PMID 35154933, 2022). "Human-vimentin immunostaining allowed the precise detection of the lung metastatic foci, which were not only formed by cancer cell clusters, but also by single cells." (PMID 35456719, 2022). "Recently, some studies have proposed vimentin as a potential molecular target for treatment of some kinds of cancers; however, our results suggest enough prudence in using it for EC." (PMID 35320951, 2022).
cancer (continued). "While vimentin has traditionally been described as an intracellular protein, an extracellular membrane-bound form has been found to be important in the context of cancer." (PMID 35257663, 2022). "For this, the main EMT hallmarks during cancer metastasis, E-cadherin and Vimentin, were examined by immunohistochemical staining of the liver." (PMID 35052775, 2022). "Bioinformatic analyses showed that RKIP was negatively correlated with vimentin in 10 cancer types (as expected) and positively correlated with 4 cancer types." (PMID 36230521, 2022). "Derivative 9f regulates the epithelial-to-mesenchymal transition (EMT) suppressing the mesenchymal marker vimentin and cancer cell migration in IL-1β-stimulated A549 cells." (PMID 35056161, 2022). "Loss of E-cadherin and increased expression of vimentin represent the hallmarks of EMT and is frequently detected in various cancers." (PMID 35876652, 2022). "IF staining of mammospheres revealed that cells maintained the epithelial cell adhesion marker (Epcam) as a marker of cancer stem cells, but lost expression of the mesenchymal cell surface marker vimentin when Pthlh was ablated." (PMID 35720668, 2022). "To identify the function of CTRP1 in cancer progression, we examined the expression levels of the metastatic markers E-cadherin and vimentin." (PMID 36139655, 2022). "Multiple studies have shown that cancer cells with coexpression of E-cadherin and vimentin led to poorer prognosis compared with those that expressed E-cadherin or vimentin alone, or neither." (PMID 36313710, 2022). "The importance of IRFA in residual cancer was also demonstrated by downregulated expression of E-cadherin and upregulated expression of N-cadherin and vimentin in the sublethally heated cells analyzed in the present study." (PMID 35033089, 2022). "After 3 passages, the cells were checked for CAFs and cancer cell markers—vimentin (VIM), alpha smooth muscle actin (α-SMA), and E-cadherin (E-CAD—by immunofluorescent staining and Western blotting." (PMID 35454913, 2022). "It has been reported that various cancer-related genes (EpCAM, VIM, and NPTN, among others) increase in these immune cells." (PMID 36012405, 2022). "In the current study, Fx significantly inhibited the expressions of N-cadherin, β-catenin, Fibronectin, and Vimentin in cancer cells, possibly by downregulating the expression of transcription factors SNAIL, ZEB, and Twist." (PMID 36160416, 2022). "Based on RT-qPCR analysis, artemisinin was also found to decrease mRNA levels of c-Myc, cyclin D1, PCNA, N-cadherin, Vimentin, and Snail, and increased mRNA levels of E-cadherin in both cancer cell lines." (PMID 35805049, 2022). "A dysfunctional JAK2/STAT3 signaling pathway can induce cancer and inhibit apoptosis, promote cancer cell migration by regulating E-cadherin and vimentin expression, and promote EMT." (PMID 36158694, 2022). "Epithelial to mesenchymal transition (EMT) promotes the aggressive behavior of cancer cells and can be characterized by E-cadherin and vimentin, which are an epithelial marker and a mesenchymal marker, respectively." (PMID 36293081, 2022). "In J82 cancer cells, the mean intensity of vimentin was higher at 24 h than at 2 h after adding NK cells (2 and 24 h; 50.09 and 81.96, respectively, P < 0.01)." (PMID 36032170, 2022). "Taken together, these findings demonstrated that actin reorganization and vimentin expression of cancer cells affected NK cell cytotoxicity." (PMID 36032170, 2022). "Consistently, immunostaining for vimentin showed that CAFs were mixed with cancer glands, which mimicked the original human cancer tissues." (PMID 35565206, 2022). "variant Indonesia and Philippines treatment groups had lower expression of IL-6, STAT3 and vimentin that imply a decrease in cell cancer survival." (PMID 37829248, 2022).
cancer (continued). "The phosphorylation of focal adhesion kinase (FAK), a transcription factor that regulates migration, was inhibited by MBZ, so it was found that the effect of MBZ regulates the migration of cancer cells through the S1P/FAK/vimentin pathway." (PMID 36500220, 2022). "Vimentin is a well-known mesenchymal protein acting as a scaffold for signaling proteins that are important for cancer cell invasion wound healing, tissue repair tissue ageing, and apoptosis." (PMID 35498535, 2022). "The presence of metastasis in the lung of these mice was confirmed by vimentin staining of cancer cells." (PMID 35192545, 2022). "The knockdown of VIM in late stage cancer serum-derived exosomes demonstrated that the migratory ability of HBECs treated by the VIM depleted exosomes was reduced, and the VIM expression in the treated HBECs was also decreased." (PMID 35158999, 2022). "14-3-3 forms autophagy-inhibitory Beclin1/14-3-3/vimentin intermediate filament complex for the pathogenesis of cancer." (PMID 35573702, 2022). "We found that immunoresistant cancer cells avoid natural killer cell-mediated cytotoxicity by upregulation of vimentin and remodeling of actin cytoskeleton." (PMID 36032170, 2022). "Vimentin was found to be significantly overexpressed in oral precancers along with cancers compared to normal tissues." (PMID 35498535, 2022). "EMT-expressing cancer cells showed decreased expression of epithelial cell markers such as E-cadherin and EpCAM, while expression of mesenchymal cell markers such as vimentin and N-cadherin increased." (PMID 35942366, 2022). "The decreased N-cadherin and Vimentin protein expression indicated that the ability of the epithelial–mesenchymal transition (EMT) of cancer cells was also weakened." (PMID 36292671, 2022). "miRNA-27a is involved in the knockdown of RKIP which contributes to a mesenchymal phenotype with the corresponding upregulation of vimentin and downregulation of E-cadherin, both being important in cancer progression and chemotherapy resistance." (PMID 36230521, 2022). "Conversely, the mesenchymal markers fibronectin and vimentin, the cancer stem cell marker CD44, the EMT‐TFs Zeb1 and Snail were all strongly increased." (PMID 35348275, 2022). "This study demonstrates the feasibility and efficacy, as well as the safety, of targeting vimentin as a cancer treatment strategy." (PMID 35606362, 2022). "Recent data suggested that vimentin intermediate filaments played an essential role in cancer cell migration, cell adhesion structures, and metastasis formation." (PMID 35281866, 2022). "LINC02470 and SMAD3 were more highly expressed in high-grade cancer cells with higher mesenchymal-like traits, such as higher N-cadherin and vimentin expression but lower E-cadherin and cytokeratin 18 expression." (PMID 35205713, 2022). "Vimentin, a major intermediate silk filament protein present in stromal cells, participates in cancer cells’ adhesion, invasion, migration and signaling by regulating the interaction between cytoskeletal proteins and cell adhesion molecules." (PMID 35745743, 2022). "After silencing vimentin, cancer cells were co-cultured with NK cells at a ratio of 1:3 for 24 h and the cancer cells were sensitive to immune cells." (PMID 36032170, 2022). "Expression of vimentin can also regulate the Slug signaling pathways for the pathogenesis of cancer." (PMID 35573702, 2022). "For cancer cells, Vimentin consequently led to metastasis and immune escape through the expression of PD-L1 in LUAD by triggering the TGF-β/SMAD2 signaling." (PMID 36119068, 2022). "One of these epithelial markers is E-Cadherin (CDH1), which is commonly described together with the mesenchymal marker VIM in the epithelial-mesenchymal transition during development and cancer." (PMID 35789843, 2022).